H1-6 (H1.6 linker histone, cluster member)
Description:
Testis-specific histone H1 that forms less compacted chromatin compared to other H1 histone subtypes. Formation of more relaxed chromatin may be required to promote chromatin architecture required for proper chromosome regulation during meiosis, such as homologous recombination. Histones H1 act as linkers that bind to nucleosomes and compact polynucleosomes into a higher-order chromatin configuration (Probable).
Synonyms: H1FT; H1T; HIST1H1T; H1.6; dJ221C16.2
Tractability: PROTAC: ubiquitination databases record sites on it.
Gene: Protein-coding gene on chromosome 6 (26,107,412 to 26,108,135, reverse strand). Ensembl gene ENSG00000187475.
Subcellular location: Nucleus; Chromosome
Gene Ontology:
Molecular function: double-stranded DNA binding; nucleosomal DNA binding; chromatin DNA binding; DNA binding; structural constituent of chromatin
Biological process: chromosome condensation; negative regulation of DNA recombination; spermatogenesis; nucleosome assembly
Cellular component: nucleus; chromatin; chromosome; nucleosome
Genetic constraint (gnomAD): Loss-of-function variants: 0 observed, 0.36 expected, observed/expected ratio (o/e) 0, 90% interval 0 to 1.86. That is too few expected variants to judge how well the gene tolerates losing a copy. Missense variants: 538 observed, 261.18 expected, observed/expected ratio (o/e) 2.06. Synonymous variants: 225 observed, 106.73 expected, observed/expected ratio (o/e) 2.11.
Homologues: Orthologues: chimpanzee H1-6 (97% identical), macaque H1-6 (89% identical), pig H1-6 (73% identical), mouse H1f6 (63% identical), tropical clawed frog XB5900552 (46% identical), zebrafish histh1l1 (46% identical), zebrafish si:dkey-108k21.10 (46% identical), zebrafish si:dkey-23a13.17 (46% identical), zebrafish histh1l3 (45% identical), zebrafish si:ch73-368j24.11 (45% identical), zebrafish si:dkey-261m9.12 (45% identical), zebrafish si:ch211-113a14.18 (45% identical), and 14 more. Paralogues in human: H1-4 (55% identical), H1-5 (53% identical), H1-2 (52% identical), H1-3 (51% identical), H1-1 (51% identical), H1-0 (33% identical), H1-8 (27% identical), H1-10 (23% identical), H1-7 (21% identical).
Diseases named in the same sentence as H1-6 in open-access papers:
H1-6 is named in the same sentence as 3 diseases in open-access papers, as found by Europe PMC text mining. Sharing a sentence is not in itself a finding about the gene and the disease. The quoted sentences say what the papers report.
cancer (4 papers, 2017 to 2023). A tumor composed of atypical neoplastic, often pleomorphic cells that invade other tissues. "H1-6 is expressed not only in the testis but also in non-germ cells such as cancer cells." (PMID 37784026, 2023).
H1-6 also shares sentences with these, for which no sentence is quoted: Infertility (1 paper); osteosarcoma (1).